PXN (paxillin)
Diseases named in the same sentence as PXN in open-access papers (continued):
Sharing a sentence is not in itself a finding about the gene and the disease.
tumor (continued). "In addition to integrin signaling, paxillin also plays a vital role in RTK mediated signaling which is especially important in tumor growth and metastasis." (PMID 26980710, 2016). "In addition, KRS appears to play regulatory roles in cell adhesion by transducing intracellular signaling to activate ERK1/2 and paxillin during cancer cell dissemination from primary tumor masses." (PMID 26091349, 2015). "Furthermore, paxillin is aberrantly regulated in various malignancies and involved in tumor growth and invasion." (PMID 25955608, 2015). "Previous studies have shown that CD147 interacts with the integrins α3β1 and α6β1 in HCC cells and activates the downstream FAK-PI3K-Ca2+ and FAK-paxillin pathways, thus contributing to the processes of cell adhesion, proliferation, differentiation, apoptosis, and tumor progression." (PMID 25428919, 2015). "Hydrogen peroxide inducible clone-5 (Hic-5), one of the paralogs of paxillin, exhibits many biological functions distinct from paxillin, but may cooperate with paxillin to trigger tumor progression." (PMID 26416447, 2015). "Furthermore, Fumos down-regulates Src activation, inhibits phosphorylation of Paxillin and prevents tumor cell invasion." (PMID 26626996, 2015). "Gastrin plays an important role in the development of multiple tumors and induces FAK and paxillin phosphorylation, suggesting that this might be a factor of tumor pathogenesis." (PMID 24885567, 2014). "PXN is a focal adhesion molecule that involved in signaling transduction and cellular migration, it can increase the adhesion between tumor cells and the surrounding extracellular matrix and molecules, thereby promotes or inhibits the tumor cell motilities." (PMID 24180516, 2013). "However, it is very interesting to observe that phospho-FAK and phospho-Paxillin are clearly seen in TGase-4 expressing tumours and virtually invisible in control tumours." (PMID 24161123, 2013). "PXN protein was mainly located in the cytoplasm of tumor cells." (PMID 24180516, 2013). "Fascin-1, ezrin or paxillin was mainly localized in the cytoplasm of tumor cells." (PMID 23209815, 2012). "We speculate that a threshold is reached in our system of LIMK1-mediated activation of FAK/paxillin/Src/AKT/Erk signaling as it contributes to tumor growth." (PMID 21682918, 2011). "Indeed, PP2 inhibitors display similar effects as observed after treatment of tumour cell lines with the experimental drugs Si135 and Si162, including inhibition of c-Src, followed by a reduced activation of cortactin and paxillin." (PMID 21152443, 2010). "Additionally, exploring the impact of CD155 and PXN expression on tumor progression could provide further insights into developing more effective treatment strategies." (PMID 40634277, 2025). "In addition, paxillin was predominantly localized within the cytoplasm of the tumor cells, and the paxillin staining index of poorly differentiated CRC was significantly higher than that of well-differentiated CRC (P < 0.001) and moderately differentiated CRC (P < 0.001)." (PMID 40861820, 2025). "Consequently, suppression of PXN expression may represent a rational therapeutic approach to surmount tumor drug resistance." (PMID 40821990, 2025). "Similarly, the high expression of paxillin in human laryngeal squamous cell carcinoma (LSCC) is associated with histopathological grade and tumor metastasis and can be used as an independent prognostic factor and an independent predictor of overall survival in patients." (PMID 37175948, 2023). "Therefore, the dysregulation of paxillin in tumor cells may lead to a reduction in cell–cell adhesion and inhibit the metastatic ability of cancer cells." (PMID 37175948, 2023). "Therefore, paxillin may be a potential target for the development of drugs to treat tumor growth and metastasis." (PMID 37175948, 2023). "However, the human pan-cancer evidence of a potential role for the PXN gene in various tumor types remains unclear." (PMID 34135128, 2021).
tumor (continued). "In addition to FAK and Pyk2, inhibition of paxillin phosphorylation decreased the tumour-targeting function of CD8+ T cells, in vitro, and paxillin knockdown reduced the adhesion and spreading of tissue-resident memory T cells (TRM) isolated from human lung tumours." (PMID 33573141, 2021). "In addition, study of in situ tumor transplantation model in nude mice showed that the suppression of SphK1 inhibited the growth of colonic orthotopic implantation tumors and the expression of paxillin, p‐paxillin, LC3 in the tumor." (PMID 34268882, 2021). "In contrast, AZD0424 produced potent inhibition of migration of human tumour cells, with evidence of inhibition of phosphorylation of the Src kinase substrate paxillin, suggesting anti-tumour effects may be due to inhibition of Src-mediated adhesion and motility signalling pathways." (PMID 29438361, 2018). "Paxillin also associates with the adapter protein 47 (GAG-CRK), a convergence molecule for signals resulting from cell adhesion as well as from the activation of growth factor receptors, which interacts with proteins involved in the regulation of the cytoskeleton and tumor metastasis." (PMID 28214467, 2017). "Furthermore, FAK-paxillin signaling pathway participates in the processes of tumor invasion and metastasis via different molecular mechanisms in many human tumors, and thus may be a potential predictor for metastasis of tumors." (PMID 26956728, 2016). "In the present study, we used cell and animal models to test the possibility that stabilization of Bcl-2 protein by phosphorylation at Serine 87 by PXN-mediated ERK activation may be responsible for tumor progression and metastasis via upregulation of MMP2 expression." (PMID 25826088, 2015). "SIRPα could also target paxillin and cofilin while inhibiting phagocytosis which is mediated by additional phagocytic receptors such as FcγR and during the phagocytosis of particles other than myelin-debris such as aging red blood cells and tumor cells." (PMID 24795566, 2014). "EphB2 is also stabilized under hypoxia by HIF-2α and promotes GBM cell invasion via paxillin phosphorylation, suggesting a HIF-2α-EphB2-paxillin axis that supports epithelial-mesenchymal transition (EMT) and tumor aggressiveness." (PMID 41200151, 2025). "To directly assess the role of this pathway in tumour cell durotaxis in vitro, we engineered the PDAC3 tumour line with human paxillin knockdown and overexpression of mutant Y31E/Y118F chicken paxillin (herein PDAC3PxnY31E/Y118F)." (PMID 40925952, 2025). "Myeloid cell trafficking to tumours depends on PI3Kγ‐mediated integrin activation, and subsequent myeloid cell recruitment and tumour inflammation depend on PLCγ, CalDAG‐GEFI and II, Rap1a, RIAM, talin, paxillin and myosin light chain kinase." (PMID 40434054, 2025). "It targets TNS3 and PXN in macrophages, while also regulating CCL2 expression in tumor cells, creating a supportive niche for tumor progression." (PMID 40647470, 2025). "Recently, a previously undisclosed role has been also unveiled, indicating that the nuclear localization of paxillin acts as a transcription factor for SRC, leading to angiogenesis and tumor growth." (PMID 38903185, 2024). "ITGB4 and PXN were involved in the modulation of VDAC1 and USP1 transcriptions, which were contributed with CDDP sensitivity and tumor proliferation." (PMID 38741195, 2024). "In summary, paxillin can directly or indirectly regulate Wnt, integrin-FAK, TGF-B, PIK3/AKT, and MAPK signaling pathways and participate in tumor invasion, metastasis, proliferation, apoptosis, and other processes." (PMID 37175948, 2023). "To this end, we stained tumor paraffin sections from patients with PDAC with NI (NI group) and without NI (no NI group) with PGP9.5, pan-CK (for labeling cancer cells) and p-paxillin." (PMID 37607005, 2023). "In melanomas, the growth and invasion activities of tumor cells were enhanced via GD3 with the effects of two specific molecules (p130Cas and paxillin)." (PMID 36824365, 2023).
tumor (continued). "NCTD can inhibit the tumor vasculogenic mimicry via suppressing MMP-2 expression and blocking the Ephrin Type a Receptor 2/Focal Adhesion Kinase/Paxillin pathway." (PMID 36463199, 2022). "We found that ECM1a promoted spheroid formation in 3D culture, tumor growth in animals, and/or expression of phosphorylated AKT, FAK, Paxillin and Rac in SKOV3, OVCA429/OVCA433, and T29 cells." (PMID 34244494, 2021). "As shown in the present study, activation of integrin αv-mediated FAK/paxillin/AKT signaling pathway was required for the proliferation, which was consistent with studies in other tumor cells that integrin αv facilitates a proliferative role." (PMID 33834020, 2021). "Further exploration demonstrated that the enhanced tumor cell migration and metastasis induced by CHD1L was mediated through ZKSCAN3-induced autophagic degradation of Paxillin." (PMID 34654797, 2021). "A recent study demonstrated that Paxillin interacts with processed LC3 through a conserved LIR motif in the amino-terminal end, and is responsible for FA turnover, tumor cell motility, and metastasis." (PMID 34654797, 2021). "Our findings revealed the downregulation of miR-137 in ESCC and its tumor suppressive role by targeting EZH2 and PXN." (PMID 33685449, 2021). "Altogether, our study showed that the ITGB1/PXN/YWHAZ/protein kinase B (AKT) axis enhances HCC progression by accelerating the cell cycle process, which offers a promising approach to halt HCC tumor growth." (PMID 34977001, 2021). "Therefore, the PXN gene may become a potential biomarker of clinical tumor prognosis." (PMID 34135128, 2021). "In summary, this study indicates that IFIX acts as a tumor suppressor and suppresses OSCC through stabilization of the cytoskeleton, through components such as cytokeratin, and by downregulating paxillin." (PMID 34599264, 2021). "As expected, IHC analysis revealed that both PXN and YWHAZ were notably upregulated in HCC tumor specimens in contrast with normal peritumoral tissues." (PMID 34977001, 2021). "Paxillin is a focal adhesion protein that promotes tumor cell proliferation, and the authors demonstrated that the oncogenic effects of MBNL3 overexpression are mediated by changes in PXN translation." (PMID 33716968, 2021). "Tandem mass spectrometric analysis presented 68 proteins were differentially expressed in LIPH‐silenced cells and LIPH‐mediated modulation of tumour cell adhesion depended on integrin‐related CAPN2 and paxillin signalling." (PMID 32618099, 2020). "LIPH suppression increased the expression of FAK p397 and paxillin, two key factors in adhesion between tumour cells, suggesting that LIPH inhibits the adhesion between tumour cells and promotes EMT through CAPN2 regulation." (PMID 32618099, 2020). "Intravenous delivery of CTNNA1 siRNA with CA nanoparticles significantly reduced tumor volume in the initial phase of the study, while siRNAs targeting CTNNB1, TLN1, VCL, PXN, and ACTN1 genes significantly decreased the tumor burden at all time points." (PMID 31269666, 2019). "All three makers were detected in most of the tumor fractions [cirRNA CCDC66 (82%, 9/11), FAK (82%, 9/11), and paxillin (91%, 10/11)]." (PMID 29855336, 2018). "Several reports have indicated that tumour cells have an active potential to induce cell migration and invasion by activating FAK/Paxillin activity." (PMID 29088796, 2017). "At a lower dose, genistein promoted tumor progression via activation of the MAPK and FAK/paxillin signaling cascades." (PMID 28423510, 2017). "We also found that STAT3 has a role in tumor angiogenesis through PXN and we discovered a new binding site for STAT3 in the PXN gene promoter, which plays an important role in inhibition of tumor angiogenesis by nobiletin." (PMID 28468300, 2017). "BCL2 BH4 domain also binds to calcineurin, CED-4, HIF-1α, c-Myc, paxillin, Raf-1, Ras and VDAC, promoting tumorigenesis or tumor survival and contributing to both anti-apoptosis and pro-tumorgenesis activities of BCL2." (PMID 27049723, 2016).
tumor (continued). "Compared with normal colon tissues, tumor tissues showed higher KRS and paxillin expression but lower E-cadherin expression, suggesting a positive correlation between KRS and paxillin (7/7) but a negative correlation between KRS and E-cadherin (4/7)." (PMID 26091349, 2015). "When using serial sections of normal and tumor colon tissues, tumor tissues identified as grade II or III clearly showed marginal and local staining for pERK1/2, whereas KRS and paxillin were observed not only in local but also in core areas." (PMID 26091349, 2015). "From the PC-3 tumour xenografts, we stained TGase-4, FAK and Paxillin using phosphospecific antibodies." (PMID 24161123, 2013). "This is in agreement with smaller patches of paxillin and vinculin observed in metastatic-derived cell lines (SW620) compared to their primary tumor-derived cell lines (SW480)." (PMID 24260200, 2013). "Additional analyses indicated that the morphological changes induced by TNFα + Estrogen + EGF in the tumor cells were accompanied by redistribution of focal adhesion kinase (FAK) and paxillin, two key regulators of cell adhesion and spreading." (PMID 24369447, 2013). "Nevertheless, expression of all three GFP-LIMK1 fusions resulted in increased FAK/paxillin/Src/AKT/Erk signaling, and increased MDA-MB-231 cellular invasion and xenograft tumor growth in nude mice." (PMID 21682918, 2011). "Given paxillin's role in FAK‐dependent cytoskeletal remodeling, its disruption may significantly impair tumor cell motility." (PMID 40497576, 2025). "While primary tumor EV promote localized ATP synthesis, and thus, faster migration, the EV from metastasizing LAM cells promote the formation of IAC through the delivery of EV pool of IAC building blocks, including vinculin, paxillin and ILK1." (PMID 40166013, 2025). "Immunohistochemical profiling of the tumour with FAK/Src and paxillin expression could have prognostic as well as therapeutic potential." (PMID 39036223, 2024). "Moreover, treatment with rCCL2 increased paxillin phosphorylation in tumor cells (mean: 3.13), while CCR4 inhibition decreased p-paxillin amounts (mean: 1.06)." (PMID 37607005, 2023). "In a recent study, pan-cancer analysis revealed that paxillin expression is not necessarily the same in different tumor types." (PMID 37175948, 2023). "Furthermore, inhibition of paxillin phosphorylation with the inhibitor 6-B345TTQ significantly reduced nerve density and tumor size in TPAC mice and cancer-nerve affinity in KPC mice." (PMID 37607005, 2023). "Meanwhile, paxillin may provide an essential link in the FAK-dependent survival pathway, which contributes to antianoikis, thereby promoting EMT and tumor metastasis." (PMID 37175948, 2023). "MiR-27b overexpression inhibited tumor growth, cell adhesion, and invasion by modulating ARFGEF1 and paxillin/c-Src axis, in HCT116 cells, and suppressed proliferation and migration in cancer stem cells by downregulating phospho-PI3K p110α and phospho-Akt expression." (PMID 36501111, 2022). "Lastly, in CR-TNBC patient P942, the baseline PDX tumor (BTY14) had high phosphorylation on the shared pTyr sites of SRC, FYN, LCK, YES1, and FGR as well as SFK substrates such as tensin, SHIP-1 (INPP5D), AFAP1L2, paxillin, and PTK2." (PMID 36077757, 2022). "Components of cellular focal adhesions such as vinculin, talin and paxillin interact with this kinase and are involved as parts of the focal adhesion complexes in the cell-ECM binding through integrins which can also be shown in spheroids used as tumor model." (PMID 34360970, 2021). "However, the impact of paxillin signalling on individual innate immune subsets in vivo and the regulation of TME within different tumour types remains to be explored." (PMID 33573141, 2021). "Furthermore, bioinformatics analysis revealed that paxillin (PXN) and 14-3-3 protein zeta (YWHAZ) are the molecules participating in ITGB1-regulated HCC tumor cell cycle progression." (PMID 34977001, 2021).
tumor (continued). "In addition to increased expression of Src, Src-Tyr 416, FAK and paxillin, we observed strong phosphorylation of FAK on Tyr 397 in tumor cells after irradiation, which is suppressed by the inhibitor and thus also reduces adhesion." (PMID 30717801, 2019). "Therefore, we indicated that TNC regulated tumour cell motility by regulating focal adhesion function via activation of multiple signalling pathways, namely JNK/Paxillin/FAK." (PMID 29088796, 2017). "Accumulating evidence reveals that tumor invasion and metastasis may be regulated by FAK/paxillin pathway." (PMID 25940440, 2015). "This is strongly supported by the observation that TGase-4 positive xenografts had activated FAK and Paxillin (pFAK and pPaxillin positive staining) on comparison to control tumours in which FAK and Paxillin were present but remain less active (less pFAK and pPaxillin staining)." (PMID 24161123, 2013). "Using this model, we found that both cytoplasmically-targeted NES-GFP-LIMK1 and nuclearly-targeted NLS-GFP-LIMK1 increased phosphorylation of cofilin, FAK, paxillin, AKT and Erk1/2, both increased cellular invasion, and both enhanced xenograft tumor growth in nude mice." (PMID 21682918, 2011). "Analysis of 161 PDAC cases from the Clinical Proteomic Tumor Analysis Consortium (CPTAC) database revealed that NAT10 mRNA expression was positively correlated with CDC42, matrix metalloproteinase-9 (MMP9), and Paxillin (PXN), which are expressed upon the focal adhesion pathway activation." (PMID 40119353, 2025). "For this study, we hypothesised that FAK, Src and paxillin proteins contribute to the genesis and progression of RCC, and therefore they are immunohistochemically expressed in the tumour tissue and positively correlate with more advanced staging and other clinicopathological features." (PMID 39036223, 2024). "Similarly, PXN expression as a continuous variable was also not significantly related to age, grade, tumor residual disease, stage and lymphatic invasion (all P > 0.05)." (PMID 36923874, 2023). "Thus, in this scenario, GSK-3 was acting as a tumor promoter and suppressing GSK-3 activity with inhibitors could reduce tumor aggressiveness by suppression of both the disassembly of paxillin and activation of FAK and RAC." (PMID 32365809, 2020). "These signaling pathways promote tumor metastasis changing the expression or activation of extracellular matrix proteases (such as MMPs), as well as cytoskeletal (cadherins, Arp2/3, N-WASP) and cell adhesion molecules (paxillin, integrins, and focal adhesion kinase)." (PMID 31649529, 2019). "Therefore, we examined whether TNC functions on tumour cell aggression and adhesion ability by activating JNK/Paxillin/FAK signalling." (PMID 29088796, 2017). "In addition, we tested p-Paxillin and FAK colocalization in the tumour cells by immunofluorescence." (PMID 29088796, 2017). "Specifically, NeoA treatment led to a delocalization of the focal adhesion scaffolding proteins paxillin and vinculin as well as a decrease in the phosphorylated form of focal adhesion kinase from characteristic longitudinal streaks at the cell-substratum interface in MDA-MB-231 tumor cells." (PMID 20520768, 2010). "QM tumour cells displayed increased phospho-FAK and phospho-paxillin Y31, whereas classical epithelial cells lacked expression or activation of this pathway, suggesting that functional mechanosensing is restricted to QM cells." (PMID 40925952, 2025). "In conclusion, miR-137 exerts tumor-suppressive functions in ESCC through forming a negative feedback loop with EZH2 and PXN." (PMID 33685449, 2021). "We provide information that tumor-derived miR-375 alters MΦ infiltration and migration by targeting TNS3 and PXN mRNA expression, without affecting polarization." (PMID 30850595, 2019).